STAT3 (signal transducer and activator of transcription 3)
Diseases named in the same sentence as STAT3 in open-access papers (continued):
Sharing a sentence is not in itself a finding about the gene and the disease.
tumor (continued). "Aberrant activation of signal transducer and activator of transcription 3 (STAT3) is associated with proliferation, metastasis and immunosuppression of the tumor cells." (PMID 39697768, 2025). "The activation of STAT3 tyrosine signaling promotes M2 ploarization of tumor-associated macrophages, while indirectly influencing EMT processes in NSCLC cells." (PMID 41376623, 2025). "STAT3 activation drives the expression of genes associated with neutrophil-mediated tumor-supportive activities, including the production of MMPs and VEGF." (PMID 40486614, 2025). "Age (≥55 years), tumor size (≥4 cm), extrathyroidal extension, larger maximum lymph node size (≥30 mm), and low n-STAT3 levels were associated with poor RFS on univariate and multivariate analyses." (PMID 41104968, 2025). "One key mechanism underlying PDLIM2’s tumor-suppressive effects involves the negative regulation of the nuclear factor kappa B (NF-κB) and signal transducer and activator of transcription 3 (STAT3) signaling pathways." (PMID 40948895, 2025). "These cytokines, in turn, sustain a suppressive TME and reinforce STAT3 signaling, forming a self-perpetuating loop that fuels both tumor growth and cachexia-associated wasting." (PMID 40704145, 2025). "In silico analysis predicted stronger interaction for the rs2242780-C allele with STAT1/STAT3 proteins that regulate a range of biological functions related to immunity and tumor suppressor activity through the JAK/STAT pathway." (PMID 40646133, 2025). "The effect of IL-22 on tumor growth was investigated by using an in vivo model of HCC: a significant increase in tumor volume was associated with enhanced phosphorylation of STAT3 as well as upregulation of cyclin D1." (PMID 40806452, 2025). "This aberrant activation has established STAT3 as a critical target for cancer therapy due to its involvement in tumor progression and association with poor disease prognosis." (PMID 40075607, 2025). "Mutations in tumor suppressor genes, which are unrelated to STAT3 activity, are what define MPM itself." (PMID 40227645, 2025). "CTLA-4 suppresses dendritic cell maturation and function by activating the extracellular signal–regulated kinase (ERK; encoded by MAPK1) and STAT3 pathways, which impairs T cell activation and anti-tumor immunity." (PMID 41550427, 2025). "With the stimulation of glucocorticoid-induced TNFR related protein (GITR), sunitinib would reprogram tumor-associated macrophages (TAMs) towards M1 polarization, which caused NK cell antitumor response via inhibiting STAT3 activity." (PMID 40052147, 2025). "This mutation intensified immune suppression by enhancing JAK2/STAT3 signaling, thereby facilitating tumor progression." (PMID 40384867, 2025). "Our findings further associate both metabolites with infections, neoplasms, and hyperphagia, showing strong binding affinities to STAT3, HSP90AA1, CASP3, CASP8, and SRC targets." (PMID 41295287, 2025). "miR-125 has been shown to play a crucial role in oncogenic upregulation and is associated with the STAT3 signalling pathway, contributing to the proliferation, migration, and invasion of the tumour cells." (PMID 39795214, 2025). "Recent investigations have revealed that a significant proportion of astrocytes identified in BMs exhibit phosphorylated (active) STAT3 (pSTAT3), indicating the importance of STAT3 signaling in tumor-associated cells." (PMID 39780275, 2025). "The anti‐tumor effects of phloridzin, acylated with docosahexaenoic acid, on Jurkat cells, were linked to activation of caspase activity, DNA fragmentation, and STAT3 phosphorylation selective down‐regulation." (PMID 40761486, 2025). "These immunosuppressive features were consistent with the ssGSEA findings, which showed enrichment of pathways associated with immunosuppressive and tumor-promoting processes, including IL-6/STAT3 signaling, TGF-β signaling, hypoxia, EMT, and angiogenesis." (PMID 40643554, 2025).
tumor (continued). "The combined effects of tumor cell p-STAT3 hyperactivation and STAT3 mRNA deficiency likely create a dual immunosuppressive axis, though future studies should dissect cell-type-specific effects using spatial transcriptomics." (PMID 40636126, 2025). "Consistent with STAT3’s established immunomodulatory functions, we systematically evaluated its association with tumor immune infiltration patterns." (PMID 40636126, 2025). "Our research indicated that ZFP14 functioned as a tumour suppressor in ccRCC by promoting the ubiquitination of signal transducer and activator of transcription 3 (STAT3), an established oncogene implicated in multiple cancers, including ccRCC." (PMID 39936533, 2025). "Stat3-mediated maintenance of NF-κB activity occurs both in cancer cells and in tumor-associated hematopoietic cells." (PMID 41160271, 2025). "NF-κB, STAT3, and Smad3 signaling have been associated with cancer-induced muscle mitochondrial dysfunction in tumor-bearing mice." (PMID 40869331, 2025). "This correlation is primarily linked to the activation of the IL-6/STAT3 signaling pathway, which plays a crucial role in tumor progression and prognosis in CRC." (PMID 41007818, 2025). "Where virus-induced chronic inflammation (mediated by NF-κB and STAT3 signaling) promotes the accumulation of somatic mutations and fosters an immunosuppressive tumor microenvironment rich in regulatory T-cells and myeloid-derived suppressor cells." (PMID 41157571, 2025). "This explains why persistent chronic inflammation itself constitutes a risk factor for certain cancers, through activation of the NF-kB and STAT3 signaling pathways associated with tumor growth." (PMID 40625889, 2025). "In melanoma, it reveals the association between ERα methylation and tumor progression, providing a theoretical basis for cancer treatment targeting acetylated STAT3." (PMID 41335282, 2025). "Tumor-induced inflammation causes DC exhaustion via the NF-kB and STAT3 signaling pathways, reducing their ability to initiate an antitumor immune response." (PMID 41176596, 2025). "Although previous studies have associated STAT3 expression, particularly in tumor cells, with adverse clinical outcomes, our results associate STAT3 expression in the immune microenvironment with better outcomes." (PMID 40426911, 2025). "Conversely, STAT3 expression showed positive correlations with immunosuppressive populations, particularly monocytes, M2-polarized macrophages, and tumor-associated neutrophils." (PMID 40636126, 2025). "Studies show the role of miR-125b in up-regulating oncogenic activity and its association with the STAT3 signaling pathway, promoting proliferation, migration, and invasion of tumor cells." (PMID 39795214, 2025). "Among them, the JAK-STAT pathway—specifically the inhibition of STAT3- is extremely associated with tumor development." (PMID 41517157, 2025). "In cancer, particularly in the TME, aberrant activation of STAT3 is widely recognized as being associated with the promotion of tumor progression." (PMID 40989587, 2025). "In primary brain tumors, tumor-associated astrocytes express STAT3 and PD-L1 at elevated levels, contributing to an immunosuppressive environment by producing additional cytokines such as IL-10 and TGF-b [180, 10972]." (PMID 39780275, 2025). "STAT3 plays a pivotal role in the expansion and activation of tumor-associated myeloid-derived suppressor cells (MDSCs)." (PMID 40069590, 2025). "The inhibition of STAT3 has also been shown to suppress tumor growth in both NF1-deficient pNFs and MPNSTs, while also reducing macrophage infiltration, inflammation, and cytokine expression, and enhancing apoptotic cell death in vivo." (PMID 41294711, 2025). "Leucine enhances mitochondrial biogenesis and activates mTOR signaling in skeletal muscle while simultaneously decreasing STAT3 phosphorylation and associated inflammatory signaling in tumor-bearing mice." (PMID 40704145, 2025).
tumor (continued). "Jak2/Stat3 in tumor-associated macrophages/myeloid cells is also crucial for inducing cancer-promoting inflammatory immune responses while inhibiting antitumor immune responses." (PMID 40801626, 2025). "Through IL‐10Rhi, IL‐10 suppresses tumor‐associated neutrophil phagocytosis via signal transducer and activator of transcription 3 (STAT3) signaling, ensuring bacterial survival." (PMID 40878391, 2025). "In HCV‐related HCC patients, overactivation of STAT3 is closely linked to tumor progression and poor prognosis, underscoring the pivotal role of JAK–STAT pathway in HCV‐induced HCC." (PMID 40060195, 2025). "Studies have indicated that the α7 nAChR present in tumor-associated macrophages has the ability to inhibit tumor metastasis via the JAK2/STAT3 signaling pathway." (PMID 38808717, 2025). "Inhibiting STAT3 can enhance the phagocytic activity of tumor-associated macrophages (TAMs) and alleviate drug resistance." (PMID 40568576, 2025). "Our group indicated the regulation of tumor inhibition by miR-124 is associated with inactivation of STAT3 and NF-κB mediated signaling transduction." (PMID 40134003, 2025). "STAT3 inhibitors function by blocking STAT3 activation in tumor cells and tumor-associated macrophages, thereby restoring antitumor immune responses and enhancing tumor suppression." (PMID 40599803, 2025). "STAT3 is heavily implicated in tumor progression, with aberrant activation observed in over 70% of human cancers." (PMID 40584128, 2025). "FABP4 is also expressed in M2-like tumor-associated macrophages and plays a critical role in pro-tumor activity by promoting the IL-6/signal transducer and activator of transcription (STAT)-3 signaling pathway in a murine breast cancer model." (PMID 40017805, 2025). "In PCa, these factors activate STAT3, NF-κB, and androgen receptor splice variant 7 (AR-V7) signaling, thereby promoting tumor-cell survival, immune evasion, and androgen desensitization, and markedly increasing proliferation." (PMID 41514658, 2025). "Hyperactivation of the STAT3 pathway is correlated with an aggressive tumor phenotype and has been implicated in cancer cell survival and proliferation." (PMID 41302515, 2025). "The STAT3/NF-κB pathway is involved in the inflammatory response associated with tumours and the inflammatory response associated with intestinal diseases." (PMID 40165931, 2025). "Herein, we investigated the expression of GCSF, GCSFR, and STAT3 genes in 21 tissue biopsy samples and also in tumor associated normal tissue (TANT) samples derived from glioblastoma patients, which revealed differential expression of these genes." (PMID 38538691, 2024). "Activation of STAT3 in cancer cells is associated with resistance to apoptosis and increased malignancy, as it promotes tumor invasion and progression." (PMID 39200479, 2024). "Intriguingly, activated STAT3 (phosphorylated STAT3) is associated with oncogenic processes, such as increased cell proliferation, inhibition of apoptosis, and tumor aggressiveness." (PMID 38612423, 2024). "We report here that E2F1 physically interacts with active STAT3 and synergistically controls IL-6 expression to induce a tumor-associated inflammatory GRN that ultimately mediates metastatic traits and modulates the TME by releasing immunomodulatory factors." (PMID 39544930, 2024). "Dysregulation of STAT3 signaling is linked to various pathological conditions, including chronic inflammation and tumor angiogenesis." (PMID 39273673, 2024). "In order to clinically translate the causal relationship between elevated STAT3 signaling activity and tumor progression in our murine KPP and KPT models, we interrogated STAD patient samples for evidence of STAT3 activity." (PMID 39128004, 2024). "In vitro cell line studies of PDAC have shown that conditioned medium from Cancer Associated Fibroblasts (CAFs) induced STAT3 expression in PDAC-3 tumor cells at the transcriptomic and protein level." (PMID 38424636, 2024).
tumor (continued). "CXCL12, secreted by cancer-associated fibroblasts (CAFs), activates the STAT3 pathway, inducing the generation and activation of myeloid-derived suppressor cells, resulting in tumor immune escape and further promoting tumor development." (PMID 38920657, 2024). "The association between B7-H4 and the JAK/STAT3 pathway has been extensively documented in various diseases, including tumours and inflammatory conditions." (PMID 39195262, 2024). "For example, treatment with STAT3 inhibitors can suppress the frequency of liver-associated MDSCs to inhibit tumor growth and dampen the suppressive function of MDSCs to enhance the anticancer efficacy of chimeric antigen receptor T (CAR-T) cells." (PMID 38397901, 2024). "STAT3 is strongly associated with malignancies and plays key roles in tumor cells, stromal cells, and tumor‐resident immune cells that regulate cancer development." (PMID 38318160, 2024). "In the HCC microenvironment, IL-6 is released by the activated NF-κB pathway, and eventually, the NF-κB/IL-6/STAT3 pathway exerts a pro-tumor effect in inflammation-associated tumors, such as HCC." (PMID 38816668, 2024). "At this point, we cannot explain why downregulation of a proposed tumor suppressor circRNA also downregulates a STAT3, whose activation is most often associated with cancer progression." (PMID 39041323, 2024). "Inflammatory cytokines, such as IL-6, IL-8, and TNF-α, secreted by tumor-associated immune cells and stromal components, activate pro-survival signaling pathways like NF-κB, STAT3, and Akt in CSCs." (PMID 38800385, 2024). "STAT3 has been linked to inflammatory changes in tumor microenvironment and to cancer cell survival." (PMID 39408743, 2024). "We concluded that abnormal proliferation was induced in cocultured mDA cells, involving the activation of the JAK/STAT3 signaling pathway and stimulation by specific cytokines and metabolites, posing a potential risk for tumor formation." (PMID 39563017, 2024). "AGER-mediated STAT3 activation induces fatty acid oxidation, causing long-chain fatty acids to break down into acetyl-CoA, polarizing macrophages into an M2-like tumor-promoting phenotype." (PMID 38965216, 2024). "The RT-qPCR analysis showed significantly decreased expression of CSC-associated markers and CXCL genes in tumor tissues of the STAT3 inhibitor–treated group, which appeared similar to YAP1 attenuation in these cell lines." (PMID 39630608, 2024). "Here, we find that lactate generated by both tumor and immune cells in the microenvironment increases the expression of CD47 and activation of STAT3 in association with reduced microglial/macrophage phagocytosis of tumor cells." (PMID 39545414, 2024). "Gain- and loss-of-function experiments revealed that VPS35 promoted tumour proliferation and metastasis via the IL-6/STAT3 pathway." (PMID 37950040, 2024). "While STAT3 is well known to be implicated in the regulation of cell cycle progression in tumor cells, its involvements in cell cycle reactivation and neuronal apoptosis in the central nervous system are less well understood." (PMID 39273571, 2024). "Previous studies have documented that the Jak2/STAT3 signaling pathway is associated with tumor metastasis and angiogenesis." (PMID 38360812, 2024). "Intriguingly, PDIA3 was found to promote an M2 macrophage phenotype in tumor-associated macrophages and increase tissue protease secretion through the STAT3/PD-1 axis." (PMID 38761176, 2024). "In comparison, it is more plausible to target the upregulated FXR in NSCLC that specifically induces the excessive or pathogenic IL-6/Jak2/STAT3 signaling pathway on the matter of tumor metastasis." (PMID 38360812, 2024). "NF-κB and STAT3 are key factors that link inflammation to cancer, likely due to their close association with the tumor-associated inflammatory environment." (PMID 38844562, 2024).
tumor (continued). "Existing studies have reported a TGF-β1–mediated association between SMAD3 and STAT3 in the regulation of hepatic or cardiac cell fibrogenesis, tumor cell fibrogenesis, and β cell dysfunction, cooperating with or antagonizing each other." (PMID 38441961, 2024). "Here we focus on the underlying mechanisms of STAT3 activation in tumor-infiltrating immune cells, which contribute to both innate and adaptive immune suppression, thereby impeding the antitumor efficacy of effector cells." (PMID 38245798, 2024). "Collectively, our results suggest that inhibition of JAK1/STAT3 pathway by p27 is associated with its tumour suppressive effect in lung carcinogenesis." (PMID 39099000, 2024). "Saponins and polysaccharides can regulate the phenotypes of tumor-associated macrophages (TAMs) by influencing signaling pathways such as TLR4/AMPK/NF-κB/STAT3 and directly modulating the expression of CD206 and VEGF." (PMID 38792234, 2024). "On the contrary, in metastatic tumours of mice deficient in HStC STAT3 (STAT3cKO), we observed an increase in the number of infiltrating CD8+ T cells and an increase in their activation state (GzmB+)." (PMID 38678021, 2024). "The constitutive activation of STAT3 is linked to tumor invasion, angiogenesis, and cell metastasis." (PMID 38786085, 2024). "MiRNAs, though indirectly implicated in STAT3 signaling, exhibit significant promise as oncogenes or tumor suppressors in this context." (PMID 38185635, 2024). "PD‐L1 expression can be induced by external stimuli, such as interferon‐γ produced by tumour cells, and intrinsic oncogenic pathways, such as STAT3 and activated EGFR mutations." (PMID 39113235, 2024). "Aberrant activation of STAT3 signals in tumor cells is tightly associated with tumor metastasis and angiogenesis." (PMID 38360812, 2024). "Tumor-associated macrophages (TAMs) can induce EMT by regulating the JAK2/STAT3/miR-506-3p/FoxQ1 axis to enhance CRC migration and invasion." (PMID 38213716, 2024). "extract that inhibited IL-10/Signal transducer and activator of transcription 3 (STAT3)/PD-L1 signaling pathway as well as shifted from the tumor-associated macrophages phenotype M2 to M1." (PMID 38500769, 2024). "A STAT3 imaging probe provides meaningful information on STAT3-associated cancer conditions and in tumor microenvironment." (PMID 38834900, 2024). "In particular, the STAT3 pathway and its associated signaling cascades have garnered substantial attention because of their critical roles in tumor development and therapeutic resistance." (PMID 39309860, 2024). "NAMPT plays a pivotal role in Tumor‐associated macrophages (TAMs) reprogramming by regulating the HIF‐1α/STAT3 and a reduction in STING activation." (PMID 38308188, 2024). "These recruited and amplified MDSCs further infiltrated the tumor tissue, and after entering the deep vascular deficiency area, the hypoxia-driven mechanism first down-regulated STAT3 and promoted the differentiation of MDSCs into TAMs." (PMID 38279145, 2024). "Activation of the IL-6/gp130/STAT3 pathway is closely associated with the proliferation, infiltration, and metastasis of tumour cells, ultimately leading to tumour progression." (PMID 38504172, 2024). "Granulocyte-macrophage colony-stimulating factor (GM-CSF), secreted by tumor cells, plays a pivotal role in cancer progression by promoting STAT3 activation in tumor-associated macrophages (TAMs) and inhibiting SHP2 activity." (PMID 38747738, 2024). "At the same time, induced release of MUC16c into the cytoplasm also promotes the secretion of IL-6, which activates the JAK2/STAT3 pathway, promotes the expression of Foxp3 in tumor tissues and the abundance of tumor-associated regulatory T cells (Tregs)." (PMID 38758220, 2024). "In the nude mouse tumour model, PXR activation was associated with the inhibition of STAT3 phosphorylation and a decrease in tumour growth rate, exhibiting differences from the findings in the CAC mouse model." (PMID 39495702, 2024).